CETP (cholesteryl ester transfer protein)
Diseases named in the same sentence as CETP in open-access papers (continued):
Sharing a sentence is not in itself a finding about the gene and the disease.
myocardial infarction (19 papers, 2012 to 2024). Gross necrosis of the myocardium, as a result of interruption of the blood supply to the area, as in coronary thrombosis. "Genetic variants of CETP have been associated with cholesterol levels, response to statins, and clinical outcomes, such as myocardial infarction or stroke." (PMID 35664336, 2022). "Associations between CETP rs9930761 and rs5883 minor variant carriers versus homozygous wild-type carriers, sex, race, and primary event (myocardial infarction, stroke or death) in INVEST." (PMID 22403620, 2012). "Additionally, two recent studies have found alleles of theCETP gene that lower hepatic CETP secretion to be associated with an increased risk of myocardial infarction." (PMID 25187879, 2014). "Studies on Caucasians and African Americans showed association of CETP variations with myocardial infarction (MI)." (PMID 27768712, 2016). "This meta-analysis aims to evaluate the relationships between seven functional polymorphisms in the CETP gene and myocardial infarction (MI) risk." (PMID 24533069, 2014). "It is well known that higher CETP activity is correlated with higher serum TG levels and myocardial infarction in patients." (PMID 29751583, 2018). "A recent meta-analysis of 11 randomized controlled trials examined the effects of CETP inhibitors on major cardiovascular events (MACE) and all-cause mortality, showing a non-significant reduction in the risk of non-fatal myocardial infarction (−7%) and death from cardiovascular causes (−8%)." (PMID 34440638, 2021).
Alzheimer disease (15 papers, 2012 to 2026). A progressive, neurodegenerative disease characterized by loss of function and death of nerve cells in several areas of the brain leading to loss of cognitive function such as memory and language. "This CETP variant and other variants identified lead to either decreased CETP expression or reduced CETP activity and associate with good cognitive performance and decreased risk of developing Alzheimer’s disease." (PMID 37533630, 2023). "Some CETP polymorphisms are connected to Alzheimer’s disease development and memory impairment, especially in patients with apoE4." (PMID 36979690, 2023). "Epidemiologically, decreased CETP activity has been associated with sustained cognitive performance during aging, longevity, and a lower risk of Alzheimer’s disease." (PMID 37533630, 2023). "An important protein regulating the distribution of cholesteryl esters in the blood is CETP, which has been linked to Alzheimer’s disease through polymorphisms." (PMID 37533630, 2023). "CETP variants with lower CETP activity have the potential to decrease Alzheimer’s disease risk, specifically in subjects carrying the APOE4 allele." (PMID 37533630, 2023). "CETP V405 homozygosity was associated with slower memory decline and lower incidence of dementia and Alzheimer disease risk in healthy older adults compared with controls in the Einstein Aging Study." (PMID 24917880, 2014). "However, all CETP inhibitors, including the novel CETP-inhibitor obicetrapib, increase plasma concentrations of apolipoprotein-E (Apo-E), which is associated with decreased risk of dementia, in particular for Alzheimer’s disease (AD)." (PMID 39415269, 2024). "Thus, the question as to whether CETP of the brain or the periphery modulates the risk of Alzheimer’s disease prevails." (PMID 37533630, 2023). "Therefore, the use of CETP inhibitors may positively impact cognitive performance, promote longevity, and decrease the risk of Alzheimer’s disease." (PMID 37533630, 2023). "Collectively, further investigations are necessary to address the potential impact of CETP inhibition in ameliorating Alzheimer’s disease symptoms." (PMID 37533630, 2023). "To set the grounds for assessing CETP inhibitors for potential drug repurposing in Alzheimer’s disease, we showed here that evacetrapib reaches brain tissue fast after intravenous injection in hCETPtg mice." (PMID 37533630, 2023). "Another healthy aging candidate gene, CETP, is a well-known regulator of HDL and has been associated with healthy aging in Ashkenazi Jewish as well as Alzheimer’s disease." (PMID 27060904, 2016). "Epidemiological studies indicated that CETP plays a disease-modifying role in Alzheimer’s disease." (PMID 37533630, 2023). "Although the exact mechanism remains unclear, CETP activity may promote Alzheimer’s disease through modifying cholesterol content, distribution, storage, or metabolism, which could be prevented by CETP inhibitors such as evacetrapib." (PMID 37533630, 2023). "Thus, hCETPtg mice present a good model for testing CETP inhibitors in the context of drug repurposing for Alzheimer’s disease." (PMID 37533630, 2023). "We conclude that evacetrapib may prove to be a good candidate to treat CETP-mediated cholesterol dysregulation in Alzheimer’s disease." (PMID 37533630, 2023). "Therefore, CETP inhibitors can be particularly useful in Alzheimer’s disease treatment." (PMID 36979690, 2023). "Thus, CETP activity in the brain could be pharmacologically reversed, which may carry the potential to delay or ameliorate Alzheimer’s disease." (PMID 37533630, 2023). "Thus, pharmacological CETP inhibitors could be repurposed for the treatment of Alzheimer’s disease as they are safe and effective at lowering CETP activity and LDL-C." (PMID 37533630, 2023). "Therefore, CETP may play an indirect modifying role in Alzheimer’s disease by affecting cholesterol of the brain." (PMID 37533630, 2023).
Alzheimer disease (continued). "Nevertheless, CETP inhibitors may be repurposed in other conditions, such as Alzheimer’s disease." (PMID 37533630, 2023). "Despite brain tissues not displaying the highest CETP expression levels, CETP that is synthesized and secreted in the brain could play an important role in the transport and the redistribution of lipids within the central nervous system and has been associated with Alzheimer’s disease risk." (PMID 34609279, 2021).
Stroke (14 papers, 2009 to 2024). Sudden impairment of blood flow to a part of the brain due to occlusion or rupture of an artery to the brain. "The results of nine of the studies were aggregated to assess the influence of CETP inhibitors on the risk of stroke in comparison to a placebo group." (PMID 38786974, 2024). "No impact of CETP inhibitors was observed on MACEs, all-cause mortality, stroke, hospitalization due to acute coronary syndrome, and revascularization." (PMID 38786974, 2024). "The authors found 5 polymorphisms (one in CETP and 1 in LIPC) that had significant interactions with statins on stroke outcome, the highest significance level was found in the CETP SNPs (rs5883), which was associated with stroke risk in simvastatin users." (PMID 22135769, 2011). "Our bioinformatics analysis results indicated that the expression levels of LIPC and its related genes (APOB, CETP, PNPLA2, and LMF1) showed significant differences between stroke and control groups." (PMID 37273686, 2023). "Based on the Gene Expression Omnibus (GEO) database analysis, significant differences in the expression levels of LIPC, APOB, CETP, PNPLA2, and LMF1 between the control and stroke groups were observed." (PMID 37273686, 2023). "Furthermore, bioinformatics analysis results demonstrated that the expression levels of LIPC and its related genes (APOB, CETP, PNPLA2, and LMF1) were significantly different between the control and stroke groups (p < 0.05), and LIPC-related proteins were mainly related to lipid metabolism." (PMID 37273686, 2023).
age-related macular degeneration (12 papers, 2015 to 2025). Age-related loss of vision in the central portion of the retina (macula), secondary to retinal degeneration. "Genetic CETP deficiency, mimicking pharmacologic CETP inhibition, is associated with a lower risk of cardiovascular morbidity and mortality but a markedly higher risk of age-related macular degeneration." (PMID 39204178, 2024). "An example of a potential safety signal is the genetic association of variants in the CETP region with age-related macular degeneration (AMD) risk." (PMID 36736292, 2023). "The present study had only a limitednumber of reported age-related macular degeneration cases, but the direction of associationwith CETP variants was consistent with previous reports." (PMID 29141072, 2018). "The CETP allele (exon 15, nucleotide A > G, rs2303790, protein D442G) was reported to be a risk factor for age-related macular degeneration, with increased levels of HDLc, in East Asians17." (PMID 29632305, 2018). "In mCNV, a recent meta-GWAS uncovered a new locus (near TEX29/LINC02337) as a shared genetic susceptibility with age-related macular degeneration (AMD), along with other risk variants at CETP and the ARMS2 regions." (PMID 40909333, 2025). "In conclusion, we provide genetic evidence that CETP is an effective target for CHD prevention but with a potential on-target adverse effect on age-related macular degeneration." (PMID 34561430, 2021). "Lipid metabolism genes such as APOE, ABCA1, LIPC, and CETP play fundamental roles in the pathogenesis of age-related macular degeneration (AMD) by influencing lipid transport, cholesterol efflux, and lipoprotein remodeling within the retinal pigment epithelium (RPE) and Bruch’s membrane." (PMID 40331961, 2025).
COVID-19 (12 papers, 2020 to 2025). A disease caused by infection with severe acute respiratory syndrome coronavirus 2. "CETP is a cholesterol metabolizing enzyme and CETP-inhibitors have been proposed as treatment option for COVID-19." (PMID 36517875, 2022). "Among them, CETP was up-regulated in the serum of asymptomatic individuals, as previously seen in COVID-19 patients with mild symptoms, while in the serum of critical patients this protein appeared down-regulated." (PMID 35397534, 2022). "Some HDL-raising pharmacological compounds have been considered as potential therapies for COVID-19, such as cholesteryl ester transfer protein (CETP)-inhibitors, recombinant cholesterol acyltransferase (LCAT)." (PMID 32892746, 2020). "Also, other HDL-raising drugs that could be considered for the treatment of COVID-19 include CETP-inhibitors, fibrates and small molecules that increase APOA-1 synthesis." (PMID 40842550, 2025). "Although the cholesterol metabolism pathway was significantly downregulated (including APOA2, APOC1, APOH, CETP, and APOA4), the increased levels of PCSK9 and APOB suggested the dysregulation of cholesterol metabolism in severe and critical COVID-19 patients." (PMID 35958562, 2022). "The markers ORM1, ORM2, S100A9, CRP, AZGP1, CFI, SERPINA3/ACT, and LCP1/LPL were significantly increased in more severe COVID-19 conditions, whereas the levels of FETUB, CETP, and PI16 were significantly decreased." (PMID 35269564, 2022). "The COVID-19 convalescents had significantly elevated immunoglobulins, Orosomucoid 2 (ORM2), peroxiredoxin-2 (PRDX2), hemoglobin subunits (HBD, HBB and HBA1), as well as proteins involved in cholesterol transport such as cholesteryl ester transfer protein (CETP) and apolipoprotein A1 (APOA1)." (PMID 38396092, 2024).
coronary atherosclerosis (11 papers, 2012 to 2023). Atherosclerosis of the coronary vasculature. "High plasma concentrations of CETP have been associated with faster progression of coronary atherosclerosis and increased carotid intima-media thickness (cIMT)." (PMID 33799675, 2021). "The aim of the present study is to evaluate the association of HDL-C-related CETP polymorphisms and risk of coronary atherosclerosis." (PMID 24283500, 2013). "Considering the crucial role of CETP in lipid metabolism, we investigated the association of seven SNPs in this gene and the risk of coronary atherosclerosis in a Chinese population." (PMID 24283500, 2013). "Considering the central role of CETP in the development of coronary atherosclerosis and its complications, we face an outstanding challenge to better understand the mechanisms associated with CETP functions." (PMID 22253581, 2012). "We investigated the association of seven single nucleotide polymorphisms (SNP) (rs1800775, rs708272, rs5882, rs1532624, rs1864163, rs7499892, and rs9989419) in the CETP gene with the risk of coronary atherosclerosis and levels of HDL-C in a case–control study in China." (PMID 24283500, 2013). "Our findings indicated that CETP rs708272 may be associated with the risk of coronary atherosclerosis and rs1800775 may influence serum HDL-C levels in healthy controls in Chinese." (PMID 24283500, 2013). "The exact mechanisms which may link CETP genetic polymorphism to coronary atherosclerosis are largely unclear." (PMID 24283500, 2013). "Coronary atherosclerosis plays a role as a mediator, accounting for 37.0% of the mediation effect for triggering the lipid-lowering effects of CETP on extended human lifespan." (PMID 38082436, 2023). "Recent studies have shown that some lipid metabolism genes, such as cholesteryl ester transfer protein (CETP) and ATP-binding cassette subfamily A member 1 (ABCA1) may indirectly cause MI by affecting coronary atherosclerosis progression." (PMID 37180972, 2023). "Interestingly, in the large secondary prevention REGRESS study, it was demonstrated that patients having a combination of defective alleles for CETP and LIPC, displayed high HDL levels but also the highest progression of coronary atherosclerosis." (PMID 23874450, 2013).
dementia (11 papers, 2012 to 2026). Loss of intellectual abilities interfering with an individual's social and occupational functions. "In a prospective cohort study, individuals homozygous for the low CETP activity V405 polymorphism demonstrated slower memory decline and a 72 % reduction in dementia risk (HR 0.28; 95 % CI, 0.10–0.85)." (PMID 41109840, 2026). "In the current study we therefore sought to elucidate the potential causal relationship between lower plasma CETP concentration and the risk of dementia and neurodegenerative diseases." (PMID 39415269, 2024). "A functional longevity‐associated allele in the cholesteryl ester transfer protein (CETP) gene, I405V, is also significantly associated with slower memory decline and lower risk for dementia and AD." (PMID 34197020, 2021). "Polymorphisms in the cholesteryl ester transfer protein (CETP) gene have been associated with exceptional longevity and lower cardiovascular risk, but associations with memory decline and dementia risk are unclear." (PMID 22482072, 2012). "Polymorphisms in the CETP gene have been associated with lower cardiovascular risk, but associations with memory decline and dementia risk are unclear." (PMID 23181436, 2012). "Consideration of dementia related traits indicated that lower CETP concentrations were associated higher total brain volume (0.04 per standard deviation, 95%CI 0.02; 0.06), lower risk of LBD (OR 0.81, 95%CI 0.74; 0.89) and Parkinson’s dementia risk (OR 0.26, 95%CI 0.14; 0.48)." (PMID 39415269, 2024). "Several studies have showed CETP gene variants such as I405V,D442G may have a potential association with memory decline and dementia risk." (PMID 23181436, 2012). "Moreover, genetic studies have linked lower CETP activity with preserved cognition and reduced dementia risk in population analyses, whereas similar protective genetic associations have not been established for 3‐hydroxy-3-methylglutaryl-CoA reductase (HMGCR) pathways." (PMID 41109840, 2026). "Providing further guidance to the current efforts expanding the CETP inhibitor obicetrapib for treatment of dementia." (PMID 39415269, 2024). "Our findings therefore call for careful re-analysis of existing (pre) clinical data on CETP inhibition, followed by potential de novo studies evaluating potential effects of CETP inhibition on dementia." (PMID 39415269, 2024). "This narrative review focuses on the role of cholesteryl ester transfer protein (CETP) and peripheral lipoproteins in the vascular contributions to cognitive impairment and dementia (VCID)." (PMID 37974180, 2023). "Consistent with known pathophysiology we expanded these analyses to show that lower CETP activity may elicit an APOE4 dependent protective effect on Lewy body dementia and dementia associated with Parkinson’s disease." (PMID 39415269, 2024). "A recent paper concluded that cholesteryl ester transfer protein (CETP) inhibition may be a viable target to treat dementia, based on human genetic evidence of a protective effect of target inhibition on risk of Lewy body and Parkinson's dementia." (PMID 39702548, 2024). "Additionally, we observed a protective effect of lower CETP against dementia in PD, which provides further evidence for CETP involvement in APOE4 driven phenotypes." (PMID 39415269, 2024). "Given that the effects of CETP on dementia are anticipated to follow from its effect on lipid metabolism, the positive control CVD effects suggest that the associations with dementia traits may be similarly robust to pre-translational horizontal pleiotropy bias." (PMID 39415269, 2024). "Also, studies in which HDL-C levels have been increased by the inhibition of cholesteryl ester transfer protein (CETP) do not appear to have influenced dementia risk." (PMID 38456089, 2024). "Thus, CETP inhibition is unlikely to be a viable target to treat the most prevalent causes of dementia." (PMID 39702548, 2024).
dementia (continued). "By contrast, for non-APOE4 carriers, the I allele, which increases CETP and decreases HDL, was associated with greater baseline thickness and lower dementia risk, suggesting that APOE genotype may modify the impact of CETP polymorphisms on neurodegeneration and cognitive decline." (PMID 37974180, 2023). "Although it has been suggested that plasma cholesterol does not have a direct effect on brain cholesterol levels [discussed in Bjorkhem and Meaney (2004)], whether it is the CETP activity in the CNS or the action of peripheral CETP which plays a role in dementia remains unclear." (PMID 37533630, 2023). "Inhibition of cholesteryl ester transfer protein (CETP) meaningfully affects the concentrations of these blood lipids and may therefore provide an opportunity to treat dementia." (PMID 39415269, 2024). "While the current analyses suggest that inhibition of CETP might protect against dementia, it does not provide information on the required dosage, timing and duration of CETP inhibition." (PMID 39415269, 2024).